TMEM278 (transmembrane protein 278)
Synonyms: TMEM88B
Tractability: Antibody: UniProt predicts a signal peptide or a membrane-spanning region; its Gene Ontology location is reachable by antibodies, with medium confidence.
Gene: Protein-coding gene on chromosome 1 (1,425,871 to 1,430,255, forward strand). Ensembl gene ENSG00000205116.
Subcellular location: Membrane
Gene Ontology:
Biological process: negative regulation of canonical Wnt signaling pathway
Cellular component: plasma membrane; membrane
Genetic constraint (gnomAD): Loss-of-function variants: 12 observed, 4.72 expected, observed/expected ratio (o/e) 2.54. That is too few expected variants to judge how well the gene tolerates losing a copy. Missense variants: 302 observed, 157.67 expected, observed/expected ratio (o/e) 1.92, 90% interval 1.73 to 1.99. Synonymous variants: 155 observed, 85.32 expected, observed/expected ratio (o/e) 1.82, 90% interval 1.59 to 1.97.
Homologues: Orthologues: macaque TMEM88B (95% identical), dog TMEM88B (79% identical), mouse Tmem88b (75% identical), pig TMEM88B (74% identical), chimpanzee TMEM88B (72% identical), rat Tmem88b (69% identical).
Diseases named in the same sentence as TMEM278 in open-access papers:
TMEM278 is named in the same sentence as 3 diseases in open-access papers, as found by Europe PMC text mining. Sharing a sentence is not in itself a finding about the gene and the disease.
TMEM278 shares sentences with these, for which no sentence is quoted: alexithymia (2 papers); cancer (1); emotional dysregulation (1).